CTSK (cathepsin K)
Diseases named in the same sentence as CTSK in open-access papers (continued):
Sharing a sentence is not in itself a finding about the gene and the disease.
prostate carcinoma (21 papers, 2008 to 2025). A carcinoma that arises from epithelial cells of the prostate gland. "The objective of the present study was to determine whether local increased bone turnover in breast and prostate cancer patients is associated with an increase in cartilage degradation and to test in vitro whether osteoclasts or cathepsin K alone generate CTXII from human bone." (PMID 18588674, 2008). "For instance, in desmoplasia-resistant prostate cancer, Cathepsin K (CTSK) accelerates tumor growth and metastasis by promoting the polarization of M2-type TAMs and modulating the TME." (PMID 39921821, 2025). "In prostate cancer, molecules downstream of CTSK act as control elements that regulate the expression of EMT-related genes and promote PC cell metastasis and hyperproliferation." (PMID 39559351, 2024). "In prostate cancer, CTSK is influenced by the CD200-CD200R axis and the IL-17 A-CTSK-EMT axis, which are involved in tumor progression and metastasis." (PMID 39736788, 2024). "High expression of CTSK enhances the invasiveness of prostate cancer cells and provides anchor points for cancer cells, playing a key role in lymph node metastasis and bone metastasis in prostate cancer." (PMID 37930479, 2023). "These proteins include MMP-9, which can be used as a biomarker for cancer; SPARC, an acidic secretory protein rich in cysteine, was positively correlated with CTSK expression and predicted a poor prognosis in prostate cancer and gastric adenocarcinoma." (PMID 36005209, 2022). "Cathepsins have an important role during tumor cell invasion and metastasis, and cathepsin K (CTSK) secreted by TAMs plays a key role in promoting prostate cancer skeletal metastasis." (PMID 32326073, 2020). "We also found that IL-20 enhances RANKL production through regulating cathepsin G and cathepsin K in prostate cancer cells." (PMID 29690863, 2018). "The active osteoclasts and the prostate cancer cells secrete the proteolytic enzyme cathepsin K to degrade the ECM and contribute to bone resorption and metastasis." (PMID 29690863, 2018). "In vitro, IL–20 upregulated N-cadherin, STAT3, vimentin, fibronectin, RANKL, cathepsin G, and cathepsin K, and increased the migration and colony formation of prostate cancer cells via activated p38, ERK1/2, AKT, and NF-κB signals in PC–3 cells." (PMID 26440411, 2015). "Cathepsin K, a cysteine protease secreted by osteoclasts and prostate cancer cells, degrades extracellular matrix during bone resorption." (PMID 26440411, 2015). "In addition, inhibition of cathepsin K has been found to inhibit the progression of prostate cancer, while improving the therapeutic effects of zoledronic acid (ZA)." (PMID 36381072, 2022). "In addition, it is well established that cathepsin K is responsible for collagen I degradation in prostate cancer bone metastasis which is necessary for tumor expansion within the bone." (PMID 31753020, 2019). "Inhibitor of cathepsin K may effectively inhibit prostate cancer metastasis and osteoclast-mediated bone resorption." (PMID 31753020, 2019). "The processes of prostate cancer (PCa) invasion and metastasis are facilitated by proteolytic cascade involving multiple proteases, such as matrix metalloproteinases, serine proteases and cysteine proteases including cathepsin K (CatK)." (PMID 31172267, 2019). "Moreover, cathepsin K is closely related to the progression of prostate cancer." (PMID 36381072, 2022). "Furthermore, cathepsin K overexpression promotes cell proliferation, migration, and invasion in non-small cell lung cancer, and cathepsin K inhibition prevents the establishment and progression of prostate cancer in bone." (PMID 34785775, 2022). "In order to characterize ongoing bone cell activity in clinical cases of prostate cancer bone metastasis, we selected a set of genes to represent osteoclast activity (ACP5, CTSK, MMP9), osteoblast activity (ALPL, BGLAP, RUNX2) and osteocytes (SOST)." (PMID 29670000, 2018).
prostate carcinoma (continued). "Similarly, cathepsin K cleaves SPARC in vitro and in vivo in its N‐terminal acid domain and in its extracellular Ca2+ binding domain in mice harboring prostate cancer bone metastases." (PMID 36346290, 2023). "Similar results were also observed in siRNA-mediated knockdown of cathepsin K. Cathepsin K siRNA decreased Raptor protein expression and phosphorylation of OTUB1 and Src in Caki-1 (renal carcinoma), A549 (lung carcinoma), and DU145 (prostate carcinoma) cells, significantly." (PMID 37330581, 2023).
rheumatoid arthritis (19 papers, 2005 to 2025). A chronic, systemic autoimmune disorder characterized by inflammation in the synovial membranes and articular surfaces. "Pharmacological inhibition of cathepsin K proteolytic activity in a mouse model of rheumatoid arthritis has been shown to reduce both bone and cartilage destruction in arthritic joints." (PMID 40332455, 2025). "As bone consists of mainly type I collagen, which is resorbed predominantly by cathepsin K, in rheumatoid arthritis (RA) and OA, there is a shift towards an MMP-driven degradation process." (PMID 38238803, 2024). "Giant cells that are formed at the later stages during rheumatoid arthritis exhibits higher concentration of cathepsin K mRNA." (PMID 35002435, 2022). "Cathepsin K, S and G serve as major target for progression of rheumatoid arthritis via degrading collagen as well as extracellular matrix." (PMID 35002435, 2022). "The major cysteine proteases which are involved in pathophysiology of joint destruction and rheumatoid arthritis comprises of cathepsin K and B. The exact and precise method of destruction in arthritis is not fully elucidated." (PMID 35002435, 2022). "The evidence which states and proves the existing role and action of cathepsin K in targeted pathogenesis of rheumatoid arthritis, are observed from pH measurements (done on deteriorating articular cartilage)." (PMID 35002435, 2022). "Under normal circumstances, expression of cathepsin K is restricted towards the fibroblast like cells and during rheumatoid arthritis, cathepsin K positive osteoclast are observed in pannus region where it invades inside bone." (PMID 35002435, 2022). "Recent studies and data have suggested the role of cathepsin K in the pathogenesis of rheumatoid arthritis." (PMID 35002435, 2022). "In patients with rheumatoid arthritis, it has been observed that cathepsin K gets localized inside the synovial fibroblast, macrophages like synoviocytes as well as in stromal multinucleated giant cells." (PMID 35002435, 2022). "Enhanced levels of cathepsin K are observed inside the synovial tissues and the joints of patients affected with rheumatoid arthritis." (PMID 35002435, 2022). "Along with this, a correlation is also studied in between the cathepsin K mRNA level and the severity of rheumatoid arthritis and osteoarthritis." (PMID 35002435, 2022). "Inhibiting cathepsin K activity could help prevent bone erosion and cartilage degradation in rheumatoid arthritis." (PMID 40332455, 2025). "In identified DEGs, we found two high degree gene in both PPI and TF-target gene networks, which were fos proto-oncogene, AP-1 transcription factor subunit (FOS) and one of top 10 up-regulated gene cathepsin K (CTSK) was involved in osteoclast differentiation and rheumatoid arthritis." (PMID 30918839, 2019). "We examined cathepsin K in the serum of 100 patients with active longstanding rheumatoid arthritis." (PMID 15642144, 2005). "However, further studies have to be performed to prove that cathepsin K is a valuable parameter for bone metabolism in patients with early rheumatoid arthritis." (PMID 15642144, 2005). "Inhibition of cathepsin K may therefore be a new target for preventing bone erosion and joint destruction in rheumatoid arthritis." (PMID 15642144, 2005). "Although the direct effect on TLR9 cleavage is not displayed, cathepsin K inhibitor inhibits TLR9 response and attenuates experimental rheumatoid arthritis in mouse model." (PMID 29997629, 2018).
melanoma (18 papers, 2009 to 2026). A malignant, usually aggressive tumor composed of atypical, neoplastic melanocytes. "On the other hand, studies on melanoma confirmed the vital role of CTSK in the acquisition of aggressive behavior by melanoma cells." (PMID 37198626, 2023). "Their results demonstrated that CTSK is consistently and strongly expressed in melanocytic lesions and has value in distinguishing malignant melanoma from most human cancers." (PMID 36005209, 2022). "In turn, the inhibition of CTSK greatly reduced the invasion of melanoma cells through the basement membrane matrix and increased the detection of internalized collagen." (PMID 36005209, 2022). "The inhibition of cathepsin K significantly reduced melanoma cell invasion and increased detection of internalized collagen in vitro." (PMID 35563798, 2022). "Studies have shown that CTSK plays a vital role in melanoma cell proliferation, migration and invasion." (PMID 36005209, 2022). "Melanomas secrete MMP and CTSK through lymph and blood to cut the internal collagen and promote melanoma cells to penetrate the dermis and realize distant metastasis." (PMID 36005209, 2022). "For example, strong expression of Cathepsin K has been observed in primary melanoma and melanoma metastases." (PMID 32927648, 2020). "The MiT family translocation RCCs commonly show weak expression of epithelial markers on immunohistochemistry and some express melanoma markers and cathepsin-K." (PMID 30123932, 2018). "The results also included 10 SNPs previously identified for melanoma risk reported at MC1R (2 SNPs), MX2, TERT/CLPTM1L, PLA2G6, CASP8, ACTRT3, ASIP, CDC91L1, and ARNT/SETDB1/LASS2ANXA9/MCL1/CTSK." (PMID 27993549, 2017). "The majority of malignant melanoma cases (10/12) showed marked cathepsin K expression in the tumor cells, while all 50 cases of cutaneous basal cell carcinoma also showed expression of this protease." (PMID 23833636, 2013). "Melanomas release CTSK and MMP to cut collagen in the intima of lymph and blood vessels." (PMID 37198626, 2023). "In a word, the role of CTSK in melanoma cannot be ignored and may be a potential target in the future." (PMID 36005209, 2022). "CTSK may mediate the degradation of matrix proteins after phagocytosis in the invasion and metastasis of melanoma." (PMID 36005209, 2022). "Similarly, cathepsin K was strongly expressed in most primary melanomas and all cutaneous melanoma metastases." (PMID 35563798, 2022). "In addition, CTSK has also shown its potential as a therapeutic target in lung cancer and melanoma and has been clinically validated." (PMID 36005209, 2022). "Tumor cells showed diffuse expression of melanocytic markers (HMB45 and melanoma cocktail), cathepsin K and TFE3 in the absence of smooth muscle markers." (PMID 41790187, 2026). "CTSK has the powerful ability to degrade the extracellular matrix (ECM), which would be beneficial for the metastasis of various human cancer types, including breast, lung, prostate and melanoma." (PMID 36005209, 2022). "The observation of a melanocyte-like phenotype was supported by the fact that shRNA-Tsc2 + Cdkn2a sphere cells that were differentiated in neural-crest differentiation medium showed similar positive staining for CATHEPSIN K, PMEL, MITF and MART-1 to the B16F1 melanoma cell line." (PMID 29133867, 2017). "These quantitative thresholds in a calibrated assay would offer some objectivity and additional specificity that is lacking when interpreting TFE3 and cathepsin K IHC in the workup of cases of ASPS for which tumors like granular cell tumor and melanoma remain in the differential consideration." (PMID 38393424, 2024).
colorectal cancer (14 papers, 2020 to 2025). A primary or metastatic malignant neoplasm that affects the colon or rectum. "Colorectal cancer is associated with high LPS secretion and overexpression of Cathepsin K." (PMID 32927648, 2020). "Cathepsin K, secreted by colorectal cancer cells, has numerous mechanistic roles in the brain, ranging from developing and maintaining the central nervous system to regulating memory and anxiety levels." (PMID 41325840, 2025). "In colorectal cancer models, it is known that tumor-secreted CTSK can bind to Toll-like receptor 4 (TLR4) on the surface of macrophages and promote M2 polarization through a mammalian target of rapamycin (mTOR)-dependent pathway." (PMID 38993570, 2024). "Microbiota has been shown to promote colorectal cancer metastasis by stimulating cathepsin K secretion and mediating TLR4-dependent M2 macrophage polarization." (PMID 38890429, 2024). "Studies on colorectal cancer also support our finding, invasion and metastasis of colorectal cancer cells promoted by CTSK that stimulates the release of cytokines such as IL10 and IL17 through activation of the mTOR pathway." (PMID 37198626, 2023). "Research on colorectal cancer revealed that CTSK is a secretory protein related to tumor metastasis and contributes to poor prognosisin vivo." (PMID 36148946, 2022). "Intestinal dysbiosis can enhance the release of LPS, which results in the production of cathepsin K (CTSK) in colorectal cancer (CRC) cells." (PMID 36046747, 2022). "LPS increased the expression of CTSK in colorectal cancer cells, which promoted the invasion and metastasis of CRC cells by stimulating the secretion of cytokines by M2 TAMs and led to a poor prognosis." (PMID 36387258, 2022). "Recently, high LPS secretion had been associated with Cathepsin K (CTSK) overexpression and secretion in colorectal cancer." (PMID 32806665, 2020). "CTSK was identified as a metastatic-related protein regulated by gut microbiota in colorectal cancers, and its effect on M2 polarization of TAMs has been confirmed." (PMID 32695142, 2020). "In colorectal cancer (CRC), CTSK can act as a mediator of intestinal microbiota imbalance leading to metastasis of CRC." (PMID 37930479, 2023). "For example, gut dysbiosis-stimulated cathepsin K secretion mediated TLR4-dependent M2 macrophage polarization and promoted tumor metastasis in colorectal cancer." (PMID 37743857, 2023).
renal cell carcinoma (13 papers, 2012 to 2025). "Indeed, cathepsin K is a recognized diagnostic tool for the identification of TFE3/TFEB-rearranged renal cell carcinoma, TFEB-amplified renal cell carcinoma, and pure epithelioid PEComa/epithelioid angiomyolipoma." (PMID 34069976, 2021). "Increasing researchers have shown that mTOR plays a crucial role in the development of renal cell carcinoma, and CTSK is closely related to the mTOR signaling pathway." (PMID 36005209, 2022). "It is reported that almost all Xp11 translocation renal cancers can express CTSK but cannot be expressed in common renal cell carcinoma as clear cell, papillary and chromophobe renal cell carcinomas." (PMID 36005209, 2022). "On the other hand, cathepsin K is positive in TFEB-rearranged renal cell carcinoma and half of TFE3-rearranged renal cell carcinoma while it is negative in clear cell renal cell carcinoma." (PMID 35980471, 2022). "The role of CTSK in renal cancers has been extensively studied, since it was first described in a translocated renal cell carcinoma in 2009." (PMID 36005209, 2022). "A panel of immunohistochemistry markers useful to distinguish TFE3/TFEB-rearranged renal cell carcinoma from other common renal cell neoplasms should include cathepsin K, CA9, CK7, and parvalbumin." (PMID 35980471, 2022). "Cathepsin K was observed in the most of MiT family translocation renal cell carcinomas (66% and 63% using the threshold of 5% and 10% or 20% positive cells respectively)." (PMID 35980471, 2022). "Cathepsin K is positive in TFEB-rearranged renal cell carcinoma and half of TFE3-rearranged renal cell carcinoma while it is negative in clear cell papillary renal cell tumor." (PMID 35980471, 2022). "Differentiating pure epithelioid PEComa/epithelioid angiomyolipoma from TFEB-rearranged renal cell carcinoma is challenging, as the two entities share the immunohistochemical expression of cathepsin K and melanocytic markers, such as HMB45 and Melan-A." (PMID 34069976, 2021). "In TFEB-rearranged renal cell carcinoma, cathepsin K staining is confirmed to be reliable, with strong and diffuse immunolabelling in the neoplastic cells, regardless of the fusion partner gene, such as MALAT1, ACTB, and NEAT1." (PMID 34069976, 2021). "Thanks to the consistent reactivity of neoplastic cells for cathepsin K in TFEB-rearranged renal cell carcinoma, it is easily distinguishable from the usual types of renal cell carcinomas." (PMID 34069976, 2021). "In the case of renal cancer, the upregulation of CtsB was shown to decrease three- and five-year patient survival rates, and CtsK was shown to be overexpressed in renal cell carcinoma patients with Xp11 translocation." (PMID 32455715, 2020). "Of note, as previously stated, immunolabelling for cathepsin K is observed in roughly half of all Xp11 translocation renal cell carcinomas." (PMID 31382581, 2019). "Staining for cathepsin K is observed in a subset of Xp11 translocation renal cell carcinomas (approximately 50%)." (PMID 31382581, 2019). "However, staining for CD10 has an important value in the differential diagnosis with TFEB-rearranged renal cell carcinoma, along with cathepsin K and CA9." (PMID 35980471, 2022). "About TFE3-rearranged renal cell carcinomas, immunolabeling was observed in roughly half of the cases (54% and 50% using the threshold of 5% and 10% or 20% positive cells respectively) whereas all the eleven TFEB-rearranged renal cell carcinomas evaluated stained positive for cathepsin K." (PMID 35980471, 2022). "These tumors may show overlapping morphological and immunohistochemical features with MiT family translocation renal cell carcinoma, especially with TFEB-rearranged renal cell carcinoma, both positive for cathepsin K and Melan-A." (PMID 35980471, 2022).